EFNB2 (ephrin B2)
Diseases named in the same sentence as EFNB2 in open-access papers (continued):
Sharing a sentence is not in itself a finding about the gene and the disease.
cancer (continued). "However, the role of the EphB4/ephrin-B2 system in other cancer cell types is controversial." (PMID 22194865, 2011). "The top 5 identified genes affecting survival negatively (p < 0.05) in at least 4/9 cancer types were LOXL2, ITGA3, ACTB, EFNB2 and ITGB1." (PMID 37206618, 2023). "The downregulation of EFNB2 and PBX1 in the cancer cells (A2780, IGROV-1 and HEC1A) with sfTSLP overexpression was confirmed by qRT-PCR." (PMID 33652749, 2021). "BBR not only could directly bind to oncogenes ephrin-B2, SIK3, and LSD1 and inactivated their functions in BC but also modulated the transcription of some cancer-related genes via directly binding to their cis-acting elements." (PMID 36119505, 2022). "We screened different cancer entities for the expression of EPHB4 and EFNB2." (PMID 35629359, 2022). "Collectively, ephrin-B2 and EphB3/4 may not mediate physical adhesion between cancer cells and fibroblasts but probably contribute to the co-invasion of the two cell types by inhibiting CIL after their interaction." (PMID 38730588, 2024). "The EPHB4 and ephrin-B2 overexpression shape, in conjunction with several other genes, a more malignant clinical phenotype, which is partially parallel to the fact that ephrin-B2′s expression correlates with the TNM Classification of Malignant Tumors (TNM) staging." (PMID 36769332, 2023). "EphB4 in cancer cells has paradoxical effects depending on whether or not its cognate ligand EFNB2 is present." (PMID 35565468, 2022). "As it has been reported that ephrin B2 induces phosphorylation of Tyr-1472 residues, we next investigated whether Tyr-1472 phosphorylation of NR2B was enhanced in the spinal cord of the mouse model of cancer-induced pain." (PMID 20979661, 2010). "However, we found that no obvious difference of VASH1 or Ephrin-B2 expression was observed between EZH2-overexpressed and EZH2-silenced NPC cells (data not shown), suggesting that the alteration of VASH1 and Ephrin-B2 induced by EZH2 was cell type dependent in cancer cells." (PMID 25237831, 2014).
infection (23 papers, 2009 to 2026). The state of being infected such as from the introduction of a foreign agent such as serum, vaccine, antigenic substance or organism. "Although NiV pseudovirus showed minimal infection in normal PK‐15 cells, NiV pseudovirus infectivity was significantly enhanced by more than 1000‐fold in PK‐15/Ephrin‐B2 #3 cells compared with that in normal PK‐15 cells." (PMID 41243593, 2026). "The infection rate showed a clear dose dependency, with the highest values observed in ephrin B2 expressing cells." (PMID 40285015, 2025). "The infection rates in both the ephrin B2 KD clone#2 and the ephrin B1/B2 dKD cells were significantly reduced compared to the control cells." (PMID 40285015, 2025). "All rCedV chimeras expressed the heterologous envelope glycoproteins in infected cells, replicated similarly in comparison to rCedV, and infection tropism was specific for ephrin-B2 and ephrin-B3 as entry receptors." (PMID 37243163, 2023). "These experiments show that SMCs are capable of fusing with cells that express ephrin-B2 on their surface, when NiV F and G are present on the membrane of SMCs, either by transfection or infection with NiV." (PMID 34070626, 2021). "Infection of endothelial cells with KSHV induces expression of Ephrin-B2, and Ephrin B2 is required for KS survival." (PMID 23209418, 2012). "The genome size (18,162 nt) and organization of CedPV is very similar to that of HeV and NiV; its nucleocapsid protein displays antigenic cross-reactivity with henipaviruses; and it uses the same receptor molecule (ephrin- B2) for entry during infection." (PMID 22879820, 2012). "The inhibitory activity of EFNB2-bearing protocells is temperature dependent; infection of cultured cells is specifically inhibited after incubation at 37°C but not at 4°C." (PMID 21390296, 2011). "Following ephrin-B2 transfection, SMCs readily fused upon infection with NiV." (PMID 34070626, 2021). "However, infection of ephrin-B2-expressing SMCs with NiV resulted in conspicuous syncytia formation by 48 h post-infection, similar to what we observe in EC cultures." (PMID 34070626, 2021). "Our in vitro study indicated that ephrin B2, but not ephrin B3, was able to restore CedPV infection in the ephrin B2-deficient HeLa cells." (PMID 22879820, 2012). "Both ephrin-B2 and ephrin-B3 are able to support productive infection of HeV and NiV, but the binding affinities of HeV and NiV-G for ephrin-B2 and -B3 are uncertain and this is also complicated by the oligomeric nature of both the G glycoprotein and the ephrins." (PMID 22470837, 2012). "In addition, the binding and infection of the henipavirus pseudotypes to target cells could be blocked by recombinant, soluble ephrin-B2 and -B3 receptors." (PMID 21073718, 2010). "Two days after infection (Day 6 ES/EB culture), cell viability and live cell yields were similar in control (uninfected and empty PGK vector-infected) and EfnB2-silenced cells." (PMID 27250641, 2016). "More importantly, within this single-cycle infection period (12 h p.i.), knockdown of either FBL or EFNB2 significantly reduced intracellular viral RNA levels relative to siNEG." (PMID 27010548, 2016). "Specifically, we tested whether pig ephrin‐B2 enhances the infectivity of an HIV‐1–based lentiviral vector pseudotyped with VSV‐G, the infection of which is mediated by endocytosis." (PMID 41243593, 2026). "Indeed, sEphrinB2-Fc inhibits GhVpp infection, binds to cell surface-expressed GhV-G31, 32 and immunoprecipitates GhV-G33, suggesting that GhV is a related African HNV that also uses ephrin B2 as an entry receptor." (PMID 25405640, 2014). "Infection of different subpopulations of PBMC did not appear to be entirely dependent on pre-existing expression of ephrin-B2, a primary receptor for NiV." (PMID 22303463, 2012). "Similarly, infection with the Cedar virus pseudotype was positively associated with the expression of EFNB1 and EFNB2 (P < 0.01), but not of EFNA2 or EFNA5." (PMID 39747691, 2025).
infection (continued). "Meanwhile, cells expressing sEFN A1 or A5 showed no signs of infection or morphological changes, further confirming EFNB2 and EFNB3 as the primary receptors critical for viral entry, whereas EFNB1 may possess a conditional, auxiliary role in mediating viral entry." (PMID 40872782, 2025). "Genomic analysis revealed that CedPV was closely related to HeV and NiV, but was distinct in its use of EFNB2, but not EFNB3 for cellular entry, and lack of pathogenicity in animal models of infection." (PMID 29587789, 2018). "Since the initial infection of NiV in SMCs is inefficient and there is no cell-to-cell fusion following infection, even at a high MOI, we hypothesized that SMCs express little or no ephrin-B2 or B3." (PMID 34070626, 2021).
retinopathy (3 papers, 2013 to 2021). "Angpt1 protein is a critical actor involved in vessel maturation since it mediates migration, adhesion and survival of endothelial cells, whereas Efnb2 protein is involved in angio-proliferative retinopathy." (PMID 24963632, 2014).
EFNB2 also shares sentences with these, for which no sentence is quoted: cardiovascular disease (3 papers); cerebral infarction (3); cholangiocarcinoma (3); leukemia (3); osteosarcoma (3); Arthritis (2); bone disorder (2); diabetic retinopathy (2); heart failure (2); irritable bowel syndrome (2); neurodegenerative disease (2); pancreatic adenocarcinoma (2); prostate tumors (2); type 2 diabetes (2); acute myocardial infarction (1); adenocarcinoma (1); adenoma (1); Alzheimer disease (1); amyotrophic lateral sclerosis (1); anterior uveitis (1); atherosclerosis (1); autoimmune disease (1); Behçet disease (1); benign prostatic hyperplasia (1); benign tumours (1); bladder tumours (1); bone cancer (1); breast tumor (1); cardiac diseases (1); cerebrovascular diseases (1).
A further 57 diseases each share a sentence with EFNB2 in 1 paper.